SENP1 (SUMO specific peptidase 1)
Diseases named in the same sentence as SENP1 in open-access papers (continued):
Sharing a sentence is not in itself a finding about the gene and the disease.
esophageal cancer (2 papers, 2021 to 2025). A primary or metastatic malignant neoplasm involving the esophagus. "Additionally, we also found significantly higher expression of SENP1 in the malignant tissues of esophageal cancer patients compared to the paired normal tissues." (PMID 38954215, 2025).
Glucose intolerance (2 papers, 2015 to 2024). Glucose intolerance (GI) can be defined as dysglycemia that comprises both prediabetes and diabetes. "Knockout of islet and β-cell SENP1, in two separate Cre-driver models, led to IP glucose intolerance after 2-day HFD associated with a loss of insulin response." (PMID 38184650, 2024). "Our present data show that adipocyte-specific SENP1-deficient mice are viable but develop the major phenotypes of T1DM, including hyperglycaemia, glucose intolerance, increases in cytotoxic T cells and autoantibody production." (PMID 26596471, 2015).
hyperglycaemia (2 papers, 2015 to 2016). "We found that hyperglycemia caused a significant decrease in the mRNA and protein of SENP1." (PMID 27110392, 2016). "The apoptosis of BRPC incubated under high glucose conditions was significantly greater than under normal glucose conditions, and this hyperglycemia-induced increase in cell apoptosis was attenuated by SENP1 overexpression." (PMID 27110392, 2016). "We also examined the levels of SENP1 mRNA and protein in the retinas of control rats (Norm) and rats that maintained hyperglycemia for eight weeks (Diab)." (PMID 27110392, 2016). "Knockdown of SENP1 promoted hyperglycemia-induced BRPC apoptosis, whereas the overexpression of SENP1 inhibited it." (PMID 27110392, 2016). "In the current study, we provided evidence that DBC1 sumoylation increased as a result of the hyperglycemia-induced inhibition of SENP1 expression in BRPCs." (PMID 27110392, 2016). "The level of hyperglycaemia observed with the GTT was prolonged in SENP1-AdipoqKO and SENP1-aP2KO mice compared with Ctrl mice." (PMID 26596471, 2015). "Consistently, HFD increased body weight and accelerated hyperglycaemia with an onset at the age of 8 weeks (versus 12 weeks under chow) in SENP1-aP2KO mice." (PMID 26596471, 2015). "Importantly, SENP1 siRNA significantly aggravated the apoptosis of BRPCs induced by hyperglycemia stress, whereas the overexpression of SENP1 inhibited cellular apoptosis." (PMID 27110392, 2016). "Specifically, HFD augments PAT morphological change, cytokine production and pancreatic damage in SENP1-aP2KO mice, and HFD augments hyperglycaemia and insulin reduction in SENP1-aP2KO mice." (PMID 26596471, 2015).
mantle cell lymphoma (2 papers, 2021 to 2024). Mantle cell lymphoma is a rare form of malignant non-Hodgkin lymphoma affecting B lymphocytes in the lymph nodes in a region called the ``mantle zone''. "In mantle cell lymphoma (MCL), SENP1 knockdown increases apoptosis by suppressing JAK-STAT5 signal transduction and increasing the expression of tumor suppressor cytokine signaling 2 (SOCS2)." (PMID 38389923, 2024).
myocardial infarction (2 papers, 2021 to 2025). Gross necrosis of the myocardium, as a result of interruption of the blood supply to the area, as in coronary thrombosis. "Given that apoptosis often accompanies hypoxia and myocardial infarction progression, we subsequently assessed the apoptosis of SENP1‐knockdown (KD) and control cells under hypoxic conditions." (PMID 40341856, 2025). "To further investigate how dysregulated SENP influences myocardial infarction, we artificially overexpressed FLAG‐tagged SENP1 in HEK293T cells and immunoprecipitated the SENP1 complex for mass spectrometry." (PMID 40341856, 2025). "Redox sensing SENPs, i.e. SENP1 and SENP3 obviously play a role in ROS dependent ischemia reperfusion injury of the heart, and a striking significance emerges for SENP2 in regulating cardiomyocyte proliferation and cardiac regeneration after myocardial infarction." (PMID 34869605, 2021).
Pan (2 papers, 2021 to 2024). "Pan cancer analysis showed that tumor patients with SENP1 high expression had a shorter survival period (HR=1.2, P<0.001) than those with low SENP1." (PMID 38822351, 2024). "In this study, genetic alterations were not important in the investigation of SENP1 carcinogenesis mechanism in the Pan-Cancer cohort." (PMID 34276383, 2021).
type 1 diabetes (2 papers, 2015 to 2022). "SENP1 has been shown to limit inflammatory response in type 1 diabetes, and fibrotic responses in liver fibrosis." (PMID 36414671, 2022). "Here the authors show that lack of the desumoylating protease SENP1 in fat tissue induces NF-κB activity and inflammation in peri-pancreatic adipocytes, leading to symptoms of type 1 diabetes in mice." (PMID 26596471, 2015).
type 2 diabetes (2 papers, 2015 to 2024). "Feeding a high-fat diet augments both type-1 and type-2 diabetes phenotypes in SENP1-deficient mice, consistent with the effects on adipocyte-derived NF-κB and cytokine signalling." (PMID 26596471, 2015). "SENP1 plays a crucial role in insulin secretion in type 2 diabetes." (PMID 39431155, 2024). "Oxidative stress-mediated inactivation of SENP1 may be a critical step in impaired insulin secretion in type 2 diabetes." (PMID 39431155, 2024).
Wilms tumor (2 papers, 2023 to 2024). An embryonal neoplasm characterized by the presence of epithelial, mesenchymal, and blastema components. "A study of Wilms tumor showed that overexpressed SENP1 dramatically increased cell proliferate capacity through stimulating Cyclin E1 expression." (PMID 38389923, 2024). "In Wilms tumor, the overall survival (OS) and disease-free survival (DFS) of patients with high SENP1 expression are dramatically shorter than those with low SENP1 expression." (PMID 38389923, 2024).
acute lymphoblastic leukemia (1 paper, 2024). Leukemia with an acute onset, characterized by the presence of lymphoblasts in the bone marrow and the peripheral blood. "In acute lymphoblastic leukemia (ALL), Topotecan was found to inhibit cells proliferation through SENP1 reduction." (PMID 38389923, 2024).
Alzheimer disease (1 paper, 2021). A progressive, neurodegenerative disease characterized by loss of function and death of nerve cells in several areas of the brain leading to loss of cognitive function such as memory and language. "The interaction of HNK with SENP1 and the functional consequences of this interaction warrant further investigation, also because SENP1 inhibitors could be useful to treat other human diseases, such as Alzheimer's disease and different CNS pathologies." (PMID 33534099, 2021).
autoimmune disease (1 paper, 2015). A disorder resulting from loss of function or tissue destruction of an organ or multiple organs, arising from humoral or cellular immune responses of the individual to their own tissue constituents. "Indeed, we detect IAA in the SENP1-aP2KO mice at old ages, indicative of autoimmune disease T1DM in these mice." (PMID 26596471, 2015).
cardiac hypertrophy (1 paper, 2024). "Our data revealed that the post‐translational SUMOylation of TEAD1 in response to cardiac hypertrophy stimulation was mediated by the deSUMOylase of SENP1." (PMID 38225750, 2024). "To provide further evidence, we assessed the relationship between TEAD1 and SENP1 in NRCM and AC16 cells during Ang II‐induced cardiac hypertrophy." (PMID 38225750, 2024). "We observed that, during cardiac hypertrophy, the modification of TEAD1 by SUMO1 was regulated by the SUMO protease SENP1." (PMID 38225750, 2024). "It is discovered that TEAD1 is modified by SUMO1 during cardiac hypertrophy and that the process of deSUMOylation is regulated by SUMO‐specific protease 1 (SENP1)." (PMID 38225750, 2024).
colorectal adenocarcinoma (1 paper, 2024). The most common type of colorectal carcinoma. "For example, in colorectal adenocarcinoma, SENP1 reduces the SUMOylation of RNF168 when DNA damage occurs, facilitating its LLPS, enhancing non-homologous end joining (NHEJ) repair efficiency, and consequently strengthening cancer cell resistance to DNA-damaging agents." (PMID 38546385, 2024).
cyst (1 paper, 2017). A sac-like closed membranous structure that may be empty or contain fluid or amorphous material. "We cannot exclude the possibility that folliculogenesis in SENP1-smKO mice might be arrested at even earlier stage, Cyst or primordial stage, or drop out of the developmental process at very early stage." (PMID 28770041, 2017).
diabetic retinopathy (1 paper, 2016). "This study investigated the role of SENP1 in pericyte loss in diabetic retinopathy." (PMID 27110392, 2016).
diffuse large B-cell lymphoma (1 paper, 2021). "We concluded that miR-138–5p in Kidney Renal Papillary Cell Carcinoma (KIRP) (R = -0.369), miR-129-1-3p in Kidney Chromophobe (KICH) (R = -0.304), and miR-129-2-3p in Lymphoid Neoplasm Diffuse Large B-cell Lymphoma (DLBC) (R = -487) have the most inhibitory effects on SENP1 expression." (PMID 34276383, 2021).
dysplasia (1 paper, 2014). A usually neoplastic transformation of the cell, associated with altered architectural tissue patterns. "Together with the fact that VPS13B does not fit well to her severe hematologic findings and bone marrow dysplasia, FLAGS helped us select SENP1 as candidate gene for our experimental validation studies." (PMID 25466818, 2014).
embryonal carcinoma (1 paper, 2026). A non-seminomatous malignant germ cell tumor characterized by the presence of large germ cells with abundant cytoplasm resembling epithelial cells, geographic necrosis, high mitotic activity, and pseudoglandular and pseudopapillary structures formation. "We also demonstrated that SUMO/sentrin-specific protease 1 (SENP1) regulates OCT4 stability and activity in embryonal carcinoma cells." (PMID 41438340, 2026).
fatty liver (1 paper, 2022). "We further investigated the role of SENP1-mediated RIPK1 suppression in the pathogenesis of NAFLD by feeding mice with HFD for 16 weeks to induce moderate hepatic steatosis, hepatic inflammation, liver damage, and fibrosis." (PMID 36414671, 2022). "Thus, liver-specific SENP1 knockout exaggerates hepatic steatosis, inflammation, fibrosis, and liver damage in an HFD-induced NAFLD mouse model in a RIPK1 kinase-dependent manner." (PMID 36414671, 2022).
fibrosis (1 paper, 2024). the formation of excess fibrous connective tissue in an organ or tissue in a reparative or reactive process. "Increased cardiac fibrosis in the cardiomyocyte-specific SENP1 deletion mice, associated with increased fibronectin (Fn) expression and secretion in cardiomyocytes, promotes fibroblast activation in response to myocardial injury." (PMID 38992961, 2024).
glomerular disorder (1 paper, 2014). A disease involving the renal glomerulus.
Hepatic fibrosis (1 paper, 2026). The presence of excessive fibrous connective tissue in the liver. "Interestingly, GA significantly modulates expression levels of SUMO1, Ubc9, and SENP1 in E. granulosus infection-driven hepatic fibrosis models, further indicating the SUMOylation pathway as a key hub of the anti-fibrotic effect of GA." (PMID 41529030, 2026). "This study demonstrates aberrant activation of the SUMOylation pathway during hepatic fibrosis progression in cystic echinococcosis (CE), characterized by upregulated SUMO1/Ubc9 expression and downregulated SENP1 in peri-cystic liver tissue." (PMID 41529030, 2026).
Hypercholesterolemia (1 paper, 2021). An increased concentration of cholesterol in the blood.
infarct (1 paper, 2021). "In addition, heterozygous SENP1 ± mice develop larger myocardial infarct lesion than control animals, altogether indicating that SENP1 might act protective against myocardial I/R injury similar to what was observed in the brain." (PMID 34869605, 2021).
Insulin resistance (1 paper, 2015). Increased resistance towards insulin, that is, diminished effectiveness of insulin in reducing blood glucose levels. "Moreover, liver insulin resistance, a hallmark of obesity-linked T2DM development, was detected under basal but more pronounced under HFD conditions in SENP1 knockout (KO) mice." (PMID 26596471, 2015). "However, HFD augments liver insulin resistance, a hallmark of obesity-linked T2DM development, in SENP1-aP2KO mice." (PMID 26596471, 2015).
invasive carcinoma (1 paper, 2017). A carcinoma that is not confined to the epithelium, and has spread to the surrounding stroma. "PTEN serves as a barrier for SENP1-mediated prostate carcinogenesis as SENP1-Tg mice develop invasive carcinomas only after PTEN reduction." (PMID 27852060, 2017). "In contrast, the SENP1-Tg and PTEN+/−bigenic mouse (PTEN+/−,Tg) has local invasive carcinoma in the anterior and dorsolateral lobes of the prostate gland of 10-month mice (red arrows) with corresponding thickening of the surrounding stroma (black arrow)." (PMID 27852060, 2017).
ischemic cardiomyopathy (1 paper, 2025). Ischemic cardiomyopathy is a cardiomyopathy in which a weakness in the muscle of the heart due to inadequate oxygen delivery to the myocardium with coronary artery disease being the most common cause. "Translating our findings, our data suggests that using AAV9‐mediated Senp1 overexpression could alleviate the progression of a murine model of ischemic cardiomyopathy (ICM), offering promise for treating patients suffering from ischemic heart disease." (PMID 40341856, 2025).
keloid (1 paper, 2023). An irregularly shaped, elevated mark on the skin caused by deposits of excessive amounts of collagen during wound healing. "In our previous study, when we inhibited sumoylation and desumoylation in keloids by silencing SUMO1 and SENP1, the regulatory effect on HKFs was related to the content of SUMO complexes but not free SUMO." (PMID 36916534, 2023).
large cell lung carcinoma (1 paper, 2025). "Small cell lung cancer (SCLC) demonstrated higher levels of SUMO1, SUMO2/3, and UBC9, whereas large cell lung carcinoma (LCC) showed markedly reduced SENP1 expression." (PMID 41268439, 2025).
malaria (1 paper, 2009). Malaria is a serious and sometimes fatal disease caused by a parasite that commonly infects a certain type of mosquito which feeds on humans. "The CPD purification system also enhanced the expression and purity of a previously uncharacterized SUMO/Sentrin-specific peptidase 1 (SENP1) from the parasitic pathogen Plasmodium falciparum, the causative agent of malaria." (PMID 19956581, 2009).
malignant lymphoma (1 paper, 2021). "We postulated that in MCL, this might be also the molecular mechanism that SENP1 regulate phosphorylation of STAT5 since there are underling similarity between lymphoid progenitor cells and malignant lymphoma cells as reported in previous literatures." (PMID 34312374, 2021).
memory impairment (1 paper, 2022). "Interestingly, the RSP has been associated not only to social memory impairments, but also to repetitive behaviours in a constitutive, neurodevelopmental Senp1-deficient mouse model." (PMID 36100669, 2022).
metastatic prostate carcinoma (1 paper, 2017). A carcinoma that arises from the prostate gland and has spread to other anatomic sites. "Therefore, SENP1 should be considered as a potential target for the treatment of advanced and metastatic prostate cancer." (PMID 28417919, 2017).
metastatic tumors (1 paper, 2026). "Immunostaining results revealed elevated levels of SENP1, OCT4, CD133, N-cadherin, and PIN1 proteins in the HBx-shCtrl group, whereas these proteins were markedly reduced in both the liver and lung metastatic tumors in the SENP1-silenced groups." (PMID 41438340, 2026).
nasopharyngeal carcinoma (1 paper, 2024). A carcinoma arising from the nasopharyngeal epithelium. "The integration of GSE12452 and GSE53819 datasets identified eleven SUMOylation regulators whose mRNA expression upregulated in nasopharyngeal carcinoma, including SENP1." (PMID 38389923, 2024). "In nasopharyngeal carcinoma, SENP1 overexpression enhances cell viability, cell proliferation rate and cell clonality." (PMID 38389923, 2024). "In nasopharyngeal carcinoma, SENP1 increases STAT1 protein level and promotes its nuclear translocation by inhibiting STAT1 SUMOylation, resulting in cancer invasion and metastasis." (PMID 38389923, 2024).
non-alcoholic fatty liver disease (1 paper, 2022). "Here the authors report that a SUMO-specific protease, SENP1, deSUMOylates RIPK1 and inhibits cell death in a mouse model of non-alcoholic fatty liver disease." (PMID 36414671, 2022).
nonalcoholic fatty liver (1 paper, 2022). "Moreover, liver-specific SENP1 knockout exaggerates hepatic inflammation and liver damage in high-fat-diet (HFD)-induced nonalcoholic fatty liver, which is suppressed by RIPK1-D138N mutation." (PMID 36414671, 2022). "Notably, genetic inhibition of RIPK1 effectively reverses disease progression in hepatocyte-specific SENP1-knockout male mice with high-fat-diet-induced nonalcoholic fatty liver." (PMID 36414671, 2022).
nonalcoholic steatohepatitis (1 paper, 2022). "We propose that deSUMOylation of RIPK1 by SENP1 provides a pathophysiologically relevant cell death-restricting checkpoint that modulates RIPK1 activation in the pathogenesis of nonalcoholic steatohepatitis." (PMID 36414671, 2022).
ovarian tumors (1 paper, 2021). "As expected, carboplatin treated ovarian tumors exhibited a significant increase of SENP1 expression." (PMID 33795649, 2021).
pancreatitis (1 paper, 2021). Inflammation of the pancreas. "Besides, SENP1 depletion in adipocytes elevated the activity of NF-κB, the production of cytokines and pancreatitis." (PMID 34035184, 2021).
premature ovarian failure (1 paper, 2017). "Consequently, the number of total follicles in adolescent and adulthood of SENP1-smKO mice maintain fewer than wild-type littermates, leading to premature ovarian failure in old (>8 months of age) SENP1-smKO mice." (PMID 28770041, 2017).
progressive multifocal leukoencephalopathy (1 paper, 2023). Progressive multifocal leukoencephalopathy (PML) is a neurological disorder that damages the myelin that covers and protects nerves in the white matter of the brain.
steatosis (1 paper, 2022). Increased lipid within the cytoplasm of cells. "We showed that hepatocyte-specific loss of SENP1 drives spontaneous NASH-related phenotypes, including liver inflammation, hepatocellular death, fibrosis, and steatosis." (PMID 36414671, 2022). "Taken together, these results suggest that the deSUMOylation activity of SENP1 is important in suppressing RIPK1 activation, and subsequent apoptosis, inflammation, and steatosis." (PMID 36414671, 2022). "We found that the protein levels of SENP1 were substantially decreased in the livers of subjects with simple steatosis or NASH, as compared to that in the nonsteatotic controls." (PMID 36414671, 2022). "SENP1-C599S but not SENP1-WT livers display apparent steatosis." (PMID 36414671, 2022).
T-cell lymphoma (1 paper, 2021). "SUMO1–3 levels are upregulated in NPM-ALK+ T-cell lymphoma cell lines and ALK+ T-cell lymphoma patient tumors, whereas SENP1 levels are significantly downregulated." (PMID 34503213, 2021). "The introduction of SENP1 expression induces deSUMOylation of NPM-ALK, and the subsequent ubiquitination and proteasomal degradation of NPM-ALK, decreasing the viability, proliferation and anchorage-independent colony formation in NPM-ALK+ T-cell lymphoma cell lines." (PMID 34503213, 2021).